DKK1 (dickkopf Wnt signaling pathway inhibitor 1)
Diseases named in the same sentence as DKK1 in open-access papers (continued):
Sharing a sentence is not in itself a finding about the gene and the disease.
Alzheimer disease (21 papers, 2012 to 2025). A progressive, neurodegenerative disease characterized by loss of function and death of nerve cells in several areas of the brain leading to loss of cognitive function such as memory and language. "Dkk-1 is associated with neuron death and Alzheimer’s disease and PAI regulates blood vessel formation, but is anti-angiogenic at high concentrations." (PMID 34111862, 2021). "DKK1 can be induced by the accumulation of amyloid β (Aβ) which is the major hallmark of Alzheimer's disease." (PMID 28507478, 2017). "Furthermore, key players in the Wnt pathway, such as DKK1 are implicated in the amyloid and tau pathologies of Alzheimer’s Disease." (PMID 35907208, 2022). "Importantly, Dkk1 mediates synaptic loss induced by Amyloid-ß, a key pathogenic molecule in Alzheimer’s disease (AD)." (PMID 24223536, 2013). "In the central nervous system, DKK1 has been associated with the pathophysiology of neuronal degeneration in Alzheimer disease (AD)." (PMID 27398238, 2012). "DKK1 can also activate the Wnt‐planar cell polarity pathway to promote neuronal death in Alzheimer's disease." (PMID 38525111, 2024). "The overexpression of DKK1 was observed in every case of Alzheimer's disease, Parkinson's disease, and cerebral ischemia." (PMID 37780577, 2023). "It is known that there is a strong association between DKK1, albumin and AD since a significantly decreased level of albumin is associated with over-expression of DKK in Alzheimer’ disease." (PMID 36291101, 2022). "This was further validated by the observation of potentiated DKK1 expression in degenerating neurons in brain samples of Alzheimer’s disease patients." (PMID 35355709, 2022). "DKK1 has been introduced as a promising therapeutic target for the treatment of Alzheimer’s disease (AD)." (PMID 35546551, 2022). "Deterioration in cognitive performance was paralleled by greater dependence in functional performance and increased neuropsychological symptoms, supporting the role of Dkk-1 in overall disease progression, particularly with established Alzheimer’s dementia." (PMID 31680933, 2019). "In Alzheimer’s disease (AD), the canonical Wnt inhibitor Dickkopf-1 (Dkk1) is induced by β-amyloid (Aβ) and shifts the balance from canonical towards non-canonical Wnt signalling." (PMID 30232325, 2018). "The objective of this exploratory study was to investigate whether circulating Dkk-1 is associated with disease progression in older adults with MCI and mild-to-moderate Alzheimer’s dementia." (PMID 31680933, 2019). "Recent data have demonstrated the increased expression of the Wnt antagonist Dickkopf-1 (DKK1) in brains of Alzheimer ́s disease (AD) patients suggesting that dysfunction of Wnt signaling could also contribute to AD pathology." (PMID 24403870, 2013). "Given that high levels of circulating Dkk-1 have been found in patients after acute ischemic stroke, these data raise the possibility that, like in Alzheimer disease, rescuing the Wnt signaling pathway might lead to neuroprotection in stroke." (PMID 22815838, 2012). "Additionally, DKK1 is under investigation as a target for intervention in Alzheimer's disease." (PMID 36929645, 2023). "Indeed, deficient Wnt signaling is causally related to increased expression of DKK1, an endogenous negative Wnt regulator, and synapse loss, both of which likely contribute to cognitive decline in Alzheimer’s disease (AD)." (PMID 36599670, 2023). "We further identify DKK1 and DKK3, involved in both Alzheimer’s disease and cancer progression, as targets of the PrPC-dependent axis." (PMID 35962130, 2022). "The downregulation of DKK1 and ADMATS1 plays a crucial role in Alzheimer’s disease." (PMID 40636521, 2025). "Studies have demonstrated a significant upregulation in the expression of Wnt signaling inhibitor proteins (such as DKK-1, SFRP-1, and SFRP-2) in postmortem AD brain and transgenic AD mouse models.This upregulation effectively suppresses the Wnt signaling pathway in Alzheimer's disease (AD)." (PMID 38041203, 2023).
ankylosing spondylitis (18 papers, 2010 to 2025). An autoimmune chronic inflammatory disorder characterized by inflammation in the vertebral joints of the spine and sacroiliac joints. "Conversely, serum-mediated suppression of Wnt signaling is reduced in patients with ankylosing spondylitis (AS), and functional DKK1 levels are strongly associated with the mechanism of ligamentous tubercle formation in AS." (PMID 38033331, 2023). "Dickkopf-1 (DKK-1), marker of bone remodelling, is also implicated in the process of syndesmophyte formation in ankylosing spondylitis." (PMID 32021963, 2020). "In the present study, we aimed to widen the toolkit of DKK-1-specific aptamers to obtain novel aptamer-based colorimetric systems for serum DKK-1 detection in patients with ankylosing spondylitis and to test the possibility of their application." (PMID 39596285, 2024). "The purpose of this study was to precisely evaluate the serum Dickkopf-1 (DKK-1) level in patients with ankylosing spondylitis (AS) relative to that in normal controls and to test the causal relationship between DKK-1 and the risk of AS." (PMID 37503346, 2023). "Herein, we aimed to address DKK1 gene expression and Wnt pathway activation in MSCs from patients with ankylosing spondylitis (AS) and explore the effect of IL-17 on MSCs with respect to DKK-1 expression and Wnt pathway activation." (PMID 35743102, 2022). "There are two controversial study reporting increased and decreased serum DKK1 levels in patients with ankylosing spondylitis." (PMID 34058801, 2021). "Recent studies show that Dickkopf-1 (DKK-1), a negative regulator of Wnt/β-catenin signalling, participates in the bone remodeling and syndesmophytes formation in ankylosing spondylitis." (PMID 32021963, 2020). "DKK-1 is known as a natural regulatory molecule of Wnt signalling, which is downregulated in ankylosing spondylitis and was shown to be crucial for the development of new syndesmophytes." (PMID 32021963, 2020). "DNA methylation of DKK‐1 may correlate with pathological bone formation in ankylosing spondylitis (AS), which may provide new strategies for the treatment of AS abnormal bone formation." (PMID 37506134, 2023). "Interestingly, in the subanalysis including studies involving patients with higher scores of structural damage, as measured by the modified stoke ankylosing spondylitis spinal score (mSASSS), Dkk-1 resulted in significantly reduced scores." (PMID 37834372, 2023). "Similarly, Wnt signaling inhibitors sclerostin and DKK-1 have been investigated as biomarkers for disease activity in ankylosing spondylitis (AS), and a lower level of serum DKK-1 was observed in AS patients." (PMID 28373995, 2017). "In humans, evidence suggests that Dkk-1 may be dysfunctional in patients with ankylosing spondylitis." (PMID 32185280, 2017).
cervical carcinoma (17 papers, 2008 to 2023). A carcinoma arising from either the exocervical squamous epithelium or the endocervical glandular epithelium. "Further more, the expression level of DKK-1 in serum was correlated with lymphatic metastasis and tumor diameter in cervical cancer and associated with the prognosis of patients with cervical cancer." (PMID 24612589, 2014). "High levels of DKK1 protein have been previously associated with cervical cancer 22; therefore, DKK1 down-regulation by PDGFBB inhibition might have anti-tumour effects, however, the potential biological role of this molecule has not yet been addressed." (PMID 25311137, 2015). "High levels of DKK1 were found in serum samples of patients with pancreas, stomach, liver, bile duct, breast, and cervical carcinoma." (PMID 31167446, 2019). "High serum levels of DKK1 were found in patients with pancreas, stomach, liver, bile duct, breast, and cervical cancers." (PMID 31167446, 2019). "The feasibility of this model is supported by experimental evidences that Dkk1 is epigenetically silenced in many tumors including gastrointestinal tumors, cervical cancers, leukemia, and medulloblastoma." (PMID 19093005, 2008). "In the present study, blockage with DKK-1, an inhibitor of Wnt/β-catenin signaling, resulted in a significant inhibition of the cervical cancer cell proliferation induced by LGR5, suggesting that LGR5 promotes cervical cancer cell proliferation via activation of the Wnt/β-catenin pathway." (PMID 25193857, 2014). "Therefore, we used DKK-1 as an antagonist and LiCl as an agonist to reverse the effects of CCAT-1 manipulation on the Wnt/β-catenin pathway in cervical cancer cells." (PMID 28978096, 2017). "In addition, a negative correlation between DKK-1 serum levels and prognosis has been suggested in non-small cell lung cancer as well as cervical carcinoma." (PMID 25182503, 2014).
non-small cell lung carcinoma (17 papers, 2013 to 2025). A group of at least three distinct histological types of lung cancer, including non-small cell squamous cell carcinoma, adenocarcinoma, and large cell carcinoma. "In addition, in non-small cell lung cancer, VM, promoted by Dickkopf-related protein 1 (DKK1) is associated with poor differentiation, advanced stage, and distant metastasis." (PMID 29112161, 2017). "This was further confirmed by the observation of much more severe bone metastasis in 470 non-small-cell lung cancer (NSCLC) patients with high serum DKK1 levels relative to control groups." (PMID 35355709, 2022). "Studies have indicated that DKK1 is oncogenic and is involved in invasive growth in non-small cell lung cancer cells." (PMID 27608843, 2016). "Moverover, DKK1 is involved in the invasion of non-small cell lung cancer, pancreatic cancer and HCC." (PMID 27608843, 2016). "In this study, we hypothesized that the increased expression of DKK1 in gefitinib-resistant non-small cell lung cancer (NSCLC) cells contributes to tumor progression." (PMID 40025612, 2025). "However, the role of DKK1 in the progression of non small cell lung cancer (NSCLC) is not fully understood." (PMID 24391982, 2013). "The significance of DKK1 as a serum protein marker for HCC and non-small cell lung cancer (NSCLC) has been investigated." (PMID 26799283, 2016). "“Linear programmed necrosis” in non-small cell lung cancer induces tumor cells to die linearly and provides space for VM formation; second, it promotes the expression of MMP2, Twist1 and Slug, promoting extracellular matrix remodeling and EMT by DKK1, which in turn promotes VM formation." (PMID 37217473, 2023).
Obesity (17 papers, 2016 to 2025). Accumulation of substantial excess body fat. "Clinical observations also show that circulating DKK1 levels are elevated in overweight/obese individuals and are associated with a higher prevalence of obesity." (PMID 41320970, 2025). "In this study, we investigated the role of DKK1 in the pathogenesis of obesity‐induced bone loss using global and tissue‐specific KO mice." (PMID 32537550, 2020). "To assess the contribution of DKK1 to the pathogenesis of obesity‐induced bone loss, we subjected Dkk1fl/fl;Rosa26‐CreERT2 (global Dkk1 cKO) mice to a HFD for 12 weeks." (PMID 32537550, 2020). "Thus, though under homeostatic conditions Dkk1 is critical for both the cortical and trabecular compartments, in obesity it drives cortical bone loss." (PMID 32537550, 2020). "Remarkably, preoperative SOST and DKK1 levels in patients with obesity were the highest among study participants." (PMID 40732944, 2025). "DKK1 expression increases during fat analysis but is lower in mature adipocytes, indicating its potential relationship with obesity." (PMID 41320970, 2025). "A decrease of DKK1 contributes to placental lipid accumulation in an obesity-prone rat model, whereas inhibiting DKK1 by siRNA decreased lipid accumulation of adipocytes in human hypertrophic obesity." (PMID 36410795, 2023). "In contrast, the mRNA levels of CXXC5 and DKK‐1, which are negative regulators of the Wnt/β‐catenin signalling, were high in the visceral adipose tissues of patients with obesity‐related T2DM." (PMID 35384342, 2022). "Obesity was induced in 8‐week‐old male mice with an inducible global (Rosa26‐CreERT2) or osteoprogenitor‐ (Osx–Cre‐) specific deletion of Dkk1 with a high‐fat diet (HFD) containing 60% fat." (PMID 32537550, 2020). "Moreover, Wnt activation has been reported to inhibit adipocyte formation, and DKK-1 overexpression can attenuate the effects of Wnt and promote lipogenesis in mice with obesity induced by a high-fat diet." (PMID 40422877, 2025). "Finally, our study findings are limited to PCOS patients living with obesity, necessitating further research to explore the variations in circulating DKK1 levels among lean PCOS patients." (PMID 41320970, 2025). "Previous research has indicated a possible connection between DKK1 and obesity." (PMID 41320970, 2025). "Additionally, we discovered that serum DKK1 levels demonstrated a positive correlation with clinical markers of obesity, biochemical indicators of glucose and lipid metabolism, and IR‐related parameters." (PMID 41320970, 2025). "Additionally, increased serum levels of Dickkopf-related protein 1 (DKK1), a known inhibitor of WNT signaling, have been associated with increased IMAT deposition in individuals with obesity and insulin resistance." (PMID 38788527, 2024). "Inhibition of DKK1 expression slows down HFD-induced obesity and improves insulin resistance." (PMID 36410795, 2023). "DKK1 is also involved in placental lipid metabolism through the canonical Wnt pathway, with significantly increased β-catenin accumulation in obesity-prone placentas compared to obesity-resistant placentas." (PMID 35355709, 2022). "We found that DKK1 plays a site‐specific role in obesity‐induced bone loss in mice, contributing to cortical, but not trabecular bone loss." (PMID 32537550, 2020). "In summary, DKK1 appears to contribute distinctly to cortical, but not trabecular bone loss in obesity." (PMID 32537550, 2020). "More importantly, osteogenic Dkk1 appears to drive cortical, but not trabecular bone loss caused by obesity." (PMID 32537550, 2020). "Our key finding was that global and osteogenic deletion of Dkk1 protected mice from obesity‐induced cortical, but not trabecular bone loss." (PMID 32537550, 2020). "Moreover, obesity would alter levels of numerous molecules, such as TNFα, DKK1, sclerostin, IL-6, serotonin, and advanced glycation end products, which could inhibit osteoblastogenesis." (PMID 40685394, 2025).
Obesity (continued). "Importantly, ANCOVA confirmed that differences in DKK1 levels among groups remained statistically significant after adjusting for BMI (p = 0.003), suggesting that the association of DKK1 with PCOS is independent of obesity‐related factors." (PMID 41320970, 2025). "For example, in DKK1 knockout mice, HFD-induced BMAT expansion is reduced, suggesting that DKK1—normally upregulated in obesity—plays a role in BMAT regulation and metabolic dysfunction." (PMID 40852589, 2025). "We also measured the levels of DKK1 and RBP4, as metabolism-related humoral factors; the levels of both these components are reported to be increased in obesity." (PMID 33120884, 2020). "In addition, DKK1 has been shown to increase the number of cells able to undergo adipogenesis by 3- to 4-fold, and this idea suggests that there may be a proportional relationship between obesity and DKK1." (PMID 27746742, 2016). "Obesity has been shown to increase levels of the Wnt inhibitors SOST and DKK1." (PMID 27746742, 2016).
type 2 diabetes (17 papers, 2014 to 2026). "Our aims were to evaluate serum DKK1 in type 2 diabetes (T2DM) patients and to analyze its relationships with cardiovascular disease (CVD)." (PMID 25369286, 2014). "Furthermore, current findings have suggested that higher levels of serum DKK1 may be associated with greater skeletal muscle adiposity, which is a fact that emerging evidence indicates that ectopic skeletal muscle adiposity may be a risk factor for type 2 diabetes." (PMID 41320970, 2025). "However, some studies argued that there was a negative correlation between bone mineralization density and serum DKK1 in type 2 diabetes." (PMID 33609082, 2021). "Finally, single-gene validation and receptor operating characteristic analysis revealed that four of these genes (MMP12, PLAU, KRT14, and DKK1) may be involved in the common pathogenetic mechanism of adamantinomatous craniopharyngioma and type 2 diabetes." (PMID 38848397, 2024). "It is important to note that non-osteogenic, patient related factors such as age, sex, type 2 diabetes mellitus (T2DM) or smoking that are known risk factors for impaired fracture healing, have been demonstrated to critically affect circulating and intra-osseus DKK1 and SOST levels." (PMID 38499638, 2024). "Age and smoking status affected the balance of DKK1 and SOST, while type 2 diabetes and sex did not demonstrate a significant influence." (PMID 38499638, 2024).